OR52I2 (olfactory receptor family 52 subfamily I member 2)
Description:
Odorant receptor.
Synonyms: OR11-12
Gene: Protein-coding gene on chromosome 11 (4,581,743 to 4,593,340, forward strand). Ensembl gene ENSG00000226288.
Subcellular location: Cell membrane
Pathways (Reactome):
Sensory Perception: Expression and translocation of olfactory receptors
Genetic constraint (gnomAD): Loss-of-function variants: 0 observed, 0.26 expected, observed/expected ratio (o/e) 0, 90% interval 0 to 1.87. That is too few expected variants to judge how well the gene tolerates losing a copy. Missense variants: 350 observed, 409.92 expected, observed/expected ratio (o/e) 0.85, 90% interval 0.78 to 0.93. Synonymous variants: 147 observed, 155.94 expected, observed/expected ratio (o/e) 0.94, 90% interval 0.82 to 1.08.
Homologues: Orthologues: chimpanzee OR52I2 (86% identical), dog OR52I1 (83% identical), mouse Or52i2 (80% identical), rat Or52i2 (77% identical). Paralogues in human: OR52I1 (95% identical), OR52B2 (45% identical), OR52E4 (42% identical), OR52D1 (42% identical), OR52E2 (42% identical), OR52J3 (42% identical), OR52E8 (41% identical), OR52B6 (41% identical), OR52K1 (41% identical), OR52K2 (41% identical), OR52E6 (41% identical), OR52H1 (41% identical), and 39 more.